RNU6-112P (RNA, U6 small nuclear 112, pseudogene)
Gene: Small nuclear RNA gene on chromosome 4 (88,275,205 to 88,275,308, reverse strand). Ensembl gene ENSG00000200469.
Homologues: Orthologues: chimpanzee U6 (99% identical), macaque U6 (93% identical), dog U6 (81% identical), pig U6 (74% identical), guinea pig U6 (60% identical). Paralogues in human: RNU6-266P (89% identical), RNU6-949P (89% identical), RNU6-842P (88% identical), RNU6-1011P (88% identical), RNU6-1024P (88% identical), RNU6-1060P (88% identical), RNU6-1181P (88% identical), RNU6-19P (88% identical), RNU6-558P (88% identical), RNU6-12P (87% identical), RNU6-13P (87% identical), RNU6-26P (87% identical), and 1288 more.